MMP3 (matrix metallopeptidase 3)
Diseases named in the same sentence as MMP3 in open-access papers (continued):
Sharing a sentence is not in itself a finding about the gene and the disease.
tumor (continued). "The overall average mRNA expression levels of Mmp3, Mmp10, and Mmp13 were higher in tumor than that in normal tissues (left)." (PMID 25742789, 2015). "Lastly, we have begun to explore potential mechanisms by which MMP3 expression influenced tumor progression." (PMID 26008967, 2015). "Altogether, in several mouse tumor models, we describe a novel transcriptional mechanism of MMP3 regulation by IRF8, and showed that MMP3 expression plays an underappreciated and key role in later stages of tumor progression, including metastasis." (PMID 26008967, 2015). "When dividing the patients into quartiles according to tumor MMP3 expression intensity (representative staining intensities), we observed an apparent distinction between the lower three quartiles and the fourth." (PMID 26807201, 2015). "Despite the fact that CMS4 cells expressed low basal levels of MMP3, silencing MMP3 further decreased tumor growth." (PMID 26008967, 2015). "In a separate cohort of mice, we collected tumor explants and verified knockdown of MMP3 expression during the course of tumor growth." (PMID 26008967, 2015). "In a previous study, we identified a significant correlation between MMP3 expression and tumor grade, where grade IV tumors showed the highest intensity staining." (PMID 26807201, 2015). "Knockdown of basal IRF8 levels in tumor cells was accompanied by enhanced MMP3 expression, while the converse held true when IRF8 was overexpressed." (PMID 26008967, 2015). "The overexpression of MMP3 in the parental CMS4 cell line model, which expressed low basal levels of MMP3, significantly enhanced tumor growth." (PMID 26008967, 2015). "EO771.LMB expressed higher levels of MMP-9 and MMP-3 that have been shown to facilitate tumour cell invasion." (PMID 25633981, 2015). "Altogether, we showed an inverse mechanistic relationship between IRF8 and MMP3 expression in tumor progression." (PMID 26008967, 2015). "Our results reveal the importance of tumor cell expression of MMP3 in all three of these tumor types for tumor progression and overall survival." (PMID 26807201, 2015). "Production of MMP3, 9 and bFGF were specifically found to be stimulated in tumor cells when cultured with media conditioned by RhoB -/- fibroblasts but repressed when RhoB -/- fibroblasts were irradiated." (PMID 25635683, 2015). "Several genes showed progressive increases during tumor growth, including Mmp2, Mmp3, Mmp13 and Mmp16, whereas Timp2 and Mmp27 showed more dynamic fluctuations in expression." (PMID 25848906, 2015). "The prediction was that if the enhanced rate of tumor growth observed with CMS4-IRF8lo cells was due at least in part to higher MMP3 levels, then attenuating MMP3 expression altogether should reduce this IRF8-dependent growth advantage." (PMID 26008967, 2015). "Altogether, these data indicated that IRF8 influenced tumor growth in part through negatively regulating MMP3 expression/function." (PMID 26008967, 2015). "More specifically, we focused on a select number of SATB1 target genes that are known to participate in tumorigenesis and metastasis (e.g. tumor/metastasis suppressors BRMS1, Kiss1, Claudin-1; tumor/metastasis promoters c-Abl, MMP3, ErbB2 and Snail)." (PMID 24260116, 2013). "More specifically, knockdown of plakoglobin in MCF-7 cells resulted in the increased mRNA and protein levels of the tumor/metastasis promoters c-Abl, Snail, ErbB2 and MMP3 and the decreased levels of tumor/metastasis suppressors BRMS1, Kiss1 and Claudin-1." (PMID 24260116, 2013). "Since MMP-2 and MMP-9 showed more tumor cell invasive activities than MMP-3, we focused on MMP-2 and -9 moving forward." (PMID 24324647, 2013). "The secreted interleukin-like Gro-alpha oncogene (CXCL1) and matrix-metalloproteinase 3 (MMP3) promote tumor initiation and growth, while chitinase 3 like-1 (CHI3L1) can protect cancer or/and stromal cells against apoptosis." (PMID 23155391, 2012).
tumor (continued). "MMP-3 expression is low in normal tissues but it is altered during tumour formation, where remodeling of the extra cellular matrix is required." (PMID 20630073, 2010). "Expression of MMP-3 was shown to be higher in stromal tissue surrounding the epithelial tumor cells than in tumor cells themselves." (PMID 19531263, 2009). "Overall, the detection of cytoplasmic MMP-13 in tumor cells, correlated significantly with the cytoplasmic MMP-3 in the peritumoral fibroblasts (p < 0.0001)." (PMID 18373849, 2008). "This indicated that tumor fibroblasts with the 5A/5A genotype secreted more MMP-3 than tumor fibroblasts with either the 6A/5A or 6A/6A genotypes (p = 0.07 and 0.009, respectively)." (PMID 17922906, 2007). "Since MMP-3 can activate other MMPs involved in mediating tumor invasion, including MMP-9, the relationship between MMP-3 genotype, IPC, and gelatinase levels in end-of-assay CM was analyzed." (PMID 17922906, 2007). "The functional importance of MMP-3 activity was demonstrated by a significant reduction in tumor cell invasion in the presence of a selective MMP-3 inhibitor." (PMID 17922906, 2007). "In vivo, MMP-3 is centrally involved in mammary gland development, and has been demonstrated to promote tumour initiation and formation in the tetracycline-regulated mouse mammary model." (PMID 16430785, 2006). "The Hs578T xenograft showed low expression of MT1-MMP (1+), MMP-1 (1+) and MMP-3 (1+) in the tumour cells." (PMID 16430785, 2006). "We analysed and compared the localised expression of MT1-MMP, MMP-1, MMP-3 and β-actin, in both the tumour parenchyma and the surrounding stroma." (PMID 16430785, 2006). "In the MDA-MB-435 cell line xenograft, we observed moderate expression of MT1-MMP and MMP-1 (2+), and high levels of MMP-3 (3+) in the tumour cells." (PMID 16430785, 2006). "In the MCF-7 xenograft, low expression of MT1-MMP, MMP-1 and MMP-3 was observed in the tumour cells (1+) as indicated by the faint purple precipitation." (PMID 16430785, 2006). "The expression of MMP-3 correlated to that of MMP-1 (P = 0.03) localized at the tumour mass and stroma of the invasive area, while MMP-2 mRNA was detected widely throughout the stroma independent of MMP-1 expression." (PMID 10362121, 1999). "Also, MMP-3 was more expressed in tumor stroma at diagnosis when compared to healthy stroma, and MMP-2 was more expressed in T cell tumors compared to B cell tumors at diagnosis." (PMID 40427122, 2025). "The reduction of KRAS may suppress matrix metalloproteinase (MMP1), MMP3, and MMP9, which are recognized as proteins associated with tumor metastasis, through a mechanism dependent on IL-17 signaling." (PMID 40486048, 2025). "For instance, MMP‐3 cytokine is an HNC oncogene that is involved in tumor remodeling." (PMID 40385549, 2025). "MMP3 is regulated by complex interactions within the tumor microenvironment (TME)." (PMID 40362252, 2025). "Additionally, MMP3 can modulate the immune response, creating an immunosuppressive environment that allows tumor cells to evade immune detection." (PMID 40362252, 2025). "MMP-3 expression is found in normal ovarian tissue and in tumour tissue." (PMID 40565125, 2025). "Similarly, we conducted correlative network analysis between the three MPs and other cell types and identified the strongest interactions between MP3 tumor cells and MMP3+ Fbs." (PMID 40126353, 2025). "Finally, we assessed the effect of multiple injections of a liposomal MMP3-siRNA formulation combined with cisplatin on tumor growth in an OC mouse model." (PMID 40362252, 2025). "However, a significant reduction in tumor growth was observed in the MMP3-siRNA plus cisplatin group compared to the NC-siRNA plus cisplatin group (* p < 0.05)." (PMID 40362252, 2025). "Moreover, in recurrent tumor tissues, this subset demonstrates a preferential interaction with MMP3+ CAFs." (PMID 40464813, 2025).
tumor (continued). "The researchers knocked out MMP3 in tumor organoids, highlighting MMP3’s dual role in tumoroid structure and EV integrity, showing that MMP3-rich EVs rescue proliferation and CD9/CD63 expression in deficient organoids, thereby positioning MMP3 as a key modulator of tumor EV function." (PMID 40806235, 2025). "Additionally, our findings suggest that MMP3 expression is influenced by the tumor microenvironment (TME), which potentially modulates immune responses and stromal interactions." (PMID 40362252, 2025). "They control metastasis formation through the secretion of transforming growth factor β (TGF-β) required for epithelial–mesenchymal transition (EMT) and angiogenesis and facilitate tumor cell migration through the secretion of MMP3, which promotes tumor cell invasion." (PMID 40136652, 2025). "Furthermore, stromal cells in the tumor microenvironment, including MMP3+IL24+ fibroblasts, APLN+ endothelial cells, and CXCL12+ pericytes, were implicated in ESCC metastasis through angiogenesis, collagen production, and inflammatory responses." (PMID 39741182, 2025). "In our integrated analysis, we discovered a unique subpopulation of tumor cells (MP3 cluster) in D‐TGCT that could regulate differentiation of CD34+ Fbs into MMP3+ Fbs and APOE+ Fbs through the COL6A3 − (ITGAV + ITGB8) ligand–receptor pair." (PMID 40126353, 2025). "Our findings revealed that some CAF subclusters were simultaneously enriched in metastatic lymph nodes and primary tumor sites, such as mCAF1 (MMP3+IL24+) and mCAF4, suggesting that these subclusters may serve as key roles in facilitating metastasis in ESCC." (PMID 39741182, 2025). "Moreover, MMP-3 was found to be strongly expressed in the peripheral borders of invasive tumor islands of OSCC samples, where collagen fibers appear to be disrupted and degraded." (PMID 39040062, 2024). "Exploring the role and mechanism of MMP3 may lead to innovative therapies to inhibit tumor invasion and metastasis effectively, enhancing patient survival and quality of life." (PMID 38720887, 2024). "Proteins associated with tumor progression or a bad prognosis such as WNT5A, MMP13, MMP3, telomerase, and NOTCH3 were upregulated while proteins associated with immune cell infiltration or pathway inhibitors/tumor suppressors such as FRZB, CD177, PPARG, and HRASLS2 were downregulated." (PMID 38504345, 2024). "This showed that MMP3 has a certain role in the tumor microenvironment of PCa." (PMID 38762659, 2024). "Notably, the tumor-promoting functions of MMP-3 appear to be more prevalent than its tumor-suppressing capabilities." (PMID 39769318, 2024). "For instance, matrix metalloproteinases (MMP1, MMP3, MMP10, MMP12), while traditionally associated with promoting tumor cell invasion and metastasis, have been shown in recent studies to facilitate ferroptosis in the right context by inducing lipid peroxidation." (PMID 39372411, 2024). "This underscores MMP3 as a multifaceted determinant crucial for tumor progression." (PMID 39431237, 2024). "However, our study provides an alternative approach for targeting MMP3 via KDM6A inhibition to prevent brain metastases of KMT2C or KMT2D mutant tumours." (PMID 38926506, 2024). "In addition, tumor-associated macrophage (M2Ф) secretes MMP-13 and MMP-3 which are involved in the promotion of metastasis via the IL-17/IL-8 axis." (PMID 36993955, 2023). "MMP3 exhibits a number of activities to promote tumor development." (PMID 36677584, 2023). "MMP3 is regulated by various miRNAs, subsequently facilitating tumor cell invasion and metastasis." (PMID 37893141, 2023). "In addition, MMP-3 is generated from plasminogen and expressed in the peri-tumoral area to facilitate tumor growth and invasion." (PMID 36839884, 2023). "MMP3 (or stromelysin 1) has a role in tumor invasion and metastasis." (PMID 36677584, 2023). "Nevertheless, MMP-3 is more commonly involved in promoting tumor development than suppressing it." (PMID 37513440, 2023).
tumor (continued). "Specifically, MMP3 is upregulated in malignant tumors and promotes tumor invasion and metastasis." (PMID 37950195, 2023). "Importantly, MMP-3 efficiently activates proMMP-9, a key player in subsequent stages of tumor progression." (PMID 37760801, 2023). "Furthermore, the expression of EMT genes and oncogenes, including Mmp3, Mmp7, Mmp8, Fn1, Vim, Foxc2, Ctnnb1, Lgr5, Axin2, cMyc, Ccnd1, and Yap1, was significantly high in the tumor of cohoused Nlrp12–/– compared with WT mice." (PMID 37581937, 2023). "The expression of the MMP3 gene, which is related to cytokines, tumor promoters, and oncogenic products, was also decreased; the effect could be a reduction in the tumor-promoting function of FoxO." (PMID 35625159, 2022). "Meanwhile, MMP3 could bind to miR-421 to decrease the functional effects of miR-421 and induce tumor metastasis." (PMID 35400271, 2022). "Mmp3 had low expression in both tumor and stroma in murine and human pancreas." (PMID 36002889, 2022). "Matrix metalloprotease-3 (MMP-3), a zinc-dependent endopeptidase, degrades several extracellular substrates and contributes to local invasion by creating a microenvironment suitable for tumor development." (PMID 36445856, 2022). "Furthermore, protein levels of MMP3 and N-cadherin in tumor tissues were suppressed while E-cadherin was upregulated." (PMID 35400271, 2022). "Together, these data support our hypothesis that vemurafenib-dependent induction of MMP1 and MMP3 is in charge of the rapid tumor cell invasion seen in SEs with the HrasA5 cells." (PMID 35174094, 2022). "It indicates that MMP1 may have a similar role to MMP3, acting only in the initial stage of tumor metastasis and appearing to be less important once metastasis occurs." (PMID 36338624, 2022). "Besides, as part of the SASP, matrix metalloproteinases (MMPs) such as MMP10, MMP12, and MMP3 can lead to cleavage of NKG2D ligands on the surface of senescent tumor cells that allows them to evade NK cell surveillance." (PMID 36330438, 2022). "We present herein extensive MMP3 expression along the pathological tumor vessels." (PMID 35216046, 2022). "Although all keratinocytes responded very similarly to vemurafenib in their expression profile, particularly with a significant induction of MMP1 and MMP3, only the HrasA5 cells revealed a vemurafenib-dependent pathophysiological shift to tumor progression, i.e., the initiation of invasive growth." (PMID 35174094, 2022). "Adipocytes are the primary cellular component of the breast tumor microenvironment; it contributes to tumor invasion and progression by the secretion of extracellular matrix (overexpression of collagen VI), production of multiple MMPs (MMP-3 and MMP-9) and proinflammatory cytokines." (PMID 33417986, 2021). "However, several studies reporting that MMP3 exhibits both tumor-promoting and tumor-inhibiting effects based on its actions on the targeted substrates." (PMID 34072157, 2021). "Our results show that only the expression of MMP-1 and MMP-3 in tumor tissue could be related to the progression of BC and suggest prioritizing these MMPs as candidates for development of therapeutic strategies in these patients." (PMID 34445715, 2021). "Structurally, MMP-3 possesses some unique characteristics and participates in the breakdown of the adherent junctions mediated by E-cadherin, which means that the tumor cells lose contact with the surrounding cells, promoting the invasion capacity of the tumor cells." (PMID 34445715, 2021). "Of note, MMP2 and MMP3 also acted as tumor promoters in five out of eight cases." (PMID 33450808, 2021). "Furthermore, in TCGA-THCA datasets, it was found that MMP3 was highly expressed in primary tumor samples." (PMID 34249125, 2021). "The addition of MMP3-rich EVs rescued tumor growth by increasing proliferating cells." (PMID 32429403, 2020).
tumor (continued). "Additionally, MET, TGFα, FGF2, CD151, and MMP3 are some of the oncogenic targets of miR-152 in human cancers; by targeting these genes, miR-152 leads to inhibition of cell proliferation and tumor metastasis." (PMID 33680048, 2020). "Our study also demonstrated that the MMP3-activated pro-drug or in vivo diagnostic probe, which could be degraded in peripheral blood, could be ineffective in the treatment and diagnosis for MMP3 over-expressed tumor types, such as NPC." (PMID 32922541, 2020). "The knockout of MMP3 significantly inhibited tumor growth in mice in the allograft model." (PMID 32260433, 2020). "MMP3 protein stained positive in 32% (63/197) tumor tissues and 3% (6/197) normal tissues." (PMID 31793228, 2020). "To elucidate the potential role of MMP3-KO in tumor progression, we examined whether the knockout of MMP3 altered the proliferation, migration, and invasion in vitro and tumor growth in vivo." (PMID 32260433, 2020). "Knockout of MMP3 markedly increased necrotic area in tumors thereby inhibiting tumor growth." (PMID 32429403, 2020). "In summary, the infusion of CAR-147 macrophages can degrade the dense collagen-based matrix that surrounds tumours, which may require the involvement of MMP3, MMP14 and MMP15." (PMID 31570753, 2019). "Interestingly, MMP3 was expressed in ~ 33% of cells in the bone marrow of tumor-bearing mice injected with MDA-MB-231GFP/Luc2 cells alone." (PMID 30813947, 2019). "By contrast, MMP3 was expressed in ~ 25% of cells in the bone marrow of tumor-bearing mice injected with MDA-MB-231GFP/Luc2 cells plus MC3T3-E1 cells and in ~ 12% of cells in the bone marrow of tumor-bearing mice injected with MDA-MB-231GFP/Luc2 cells plus EO-231 cells." (PMID 30813947, 2019). "Immunostaining with an MMP-3 antibody revealed a predominantly positive-stained region located between the tumor mass and surrounding connective tissue, which was colocalized with the positive signal obtained by using the MMP-3-sensitive probe and NIRF imaging (respectively)." (PMID 29390034, 2018). "By contrast, our data demonstrated that the synthesized MMP-3-sensitive probe could specifically detect increased MMP-3 activity not only in cell cultures but also in tumor-bearing mice in situ." (PMID 29390034, 2018). "The detection of MMP-3 activity at day 5, which subsequently decreased, implies that this molecule may have a “hit-and-run” a role during early-stage tumor growth and suggests that MMP-3 could be a potential molecular target for the early detection of EOC." (PMID 29390034, 2018). "Therefore, MMP3 likely weakly promotes tumor invasion by itself but mainly acts through activation of other MMPs, such as MMP9, in 3LL cells." (PMID 29137230, 2017). "However, the tumors grew independent of MMP3 expression after initial formation, suggesting that MMP3 is important during initial tumor development." (PMID 26956475, 2016). "Additionally, treatment with sorafenib largely blunted the transcriptional activities of MMP1 and MMP3 (p < 0.05), which are required to mediate cell invasion during wound repair and even tumor metastasis." (PMID 27339758, 2016). "Reports also indicate the up-regulation of MMP2, MMP3, and/or MMP9 to be associated with tumor aggressiveness, suggesting that SIBLING-MMP complexes may facilitate tumor cell metastasis." (PMID 27331624, 2016). "Thus we noticed a tumor nuclear reactivity for all MMPs but with high intensity especially for MMP-3 and MMP-9, which were also expressed in the cytoplasm and within amyloid deposits." (PMID 27871286, 2016). "Another stromelysin, MMP-3 is induced in the tumor stroma in the early stages of tumorigenesis." (PMID 27271600, 2016). "Moreover, recent work by Bissell, Werb and colleagues demonstrated a functional role for MMP3 during hypermorphic epithelial outgrowth via effects on mammary stem cells, which reinforces the relevance of MMP3 during tumor initiation/promotion." (PMID 26008967, 2015).